RASSF3 (Ras association domain family member 3)
Tractability: Antibody: its Gene Ontology location is reachable by antibodies, with high confidence. PROTAC: ubiquitination databases record sites on it.
Gene: Protein-coding gene on chromosome 12 (64,507,001 to 64,697,567, forward strand). Ensembl gene ENSG00000153179.
Subcellular location: Cytoplasm; Cytoplasm, cytoskeleton
Subcellular location (Human Protein Atlas): Cytosol; Plasma membrane
Gene Ontology:
Molecular function: identical protein binding; protein binding
Biological process: signal transduction
Cellular component: cytosol; cytoplasm; cytoskeleton
Genetic constraint (gnomAD): Loss-of-function variants: 12 observed, 11.62 expected, observed/expected ratio (o/e) 1.03, 90% interval 0.66 to 1.64. The upper end of that interval is the gene's LOEUF score, 1.64, which puts it in group 6 of 6, group 1 being the genes least tolerant of losing a copy. Missense variants: 256 observed, 239.73 expected, observed/expected ratio (o/e) 1.07, 90% interval 0.96 to 1.18. Synonymous variants: 100 observed, 92.36 expected, observed/expected ratio (o/e) 1.08, 90% interval 0.92 to 1.28.
Homologues: Orthologues: pig RASSF3 (95% identical), mouse Rassf3 (92% identical), rat Rassf3 (91% identical), chimpanzee RASSF3 (89% identical), macaque RASSF3 (87% identical), dog RASSF3 (82% identical), guinea pig RASSF3 (79% identical), tropical clawed frog rassf3 (65% identical), zebrafish rassf3 (53% identical), Caenorhabditis elegans rsf-1 (31% identical), Drosophila melanogaster Rassf (21% identical). Paralogues in human: RASSF5 (46% identical), RASSF1 (39% identical), RASSF4 (22% identical), RASSF2 (21% identical), RASSF6 (20% identical).
Diseases named in the same sentence as RASSF3 in open-access papers:
RASSF3 is named in the same sentence as 17 diseases in open-access papers, as found by Europe PMC text mining. Sharing a sentence is not in itself a finding about the gene and the disease. The quoted sentences say what the papers report.
breast cancer (5 papers, 2013 to 2021). A primary or metastatic malignant neoplasm involving the breast. "RASSF3 is considered to be responsible in part for resistance to mammary tumor development in neu transgenic mice." (PMID 23555615, 2013). "RASSF3 was previously shown to inhibit cell proliferation in breast cancer cell lines." (PMID 24367615, 2013). "RASSF3 is a Ras-dependent proapoptotic protein that is frequently found transcriptionally silenced in many cancers including in 24% of NSCLC and has been identified in a screen for genes that suppress MMTV-Neu-driven breast cancer." (PMID 24489653, 2014).
colorectal cancer (2 papers, 2017 to 2020). A primary or metastatic malignant neoplasm that affects the colon or rectum. "In particular, RASSF1A, RASSF3, and methylation have been associated with colorectal cancer development, although the mechanisms of action remain poorly understood." (PMID 32883271, 2020). "RASSF1 and RASSF3 have been considered as potential biomarkers and for the development of new targeted therapies for colorectal cancer." (PMID 32883271, 2020). "Three of these genes (Rgs16, Rassf3 and Fam13a) are members of the RAC/RHO/RAS pathway, and dysregulated Rgs16 has been associated with poor prognosis in colorectal cancer." (PMID 28219480, 2017).
somatotroph adenomas (2 papers, 2013 to 2015). "Regarding RASSF3 and RASSF4, very little data exist, but it was reported that RASSF3 is epigenetically inactivated in somatotroph adenomas and RASSF4 in human tumor cells." (PMID 25750636, 2015). "RASSF3 was found with frequent methylation of CpG island in its promoter region in somatotroph adenomas but rarely in adenohypophyses." (PMID 23555615, 2013). "We also investigated RASSF3 expression level in somatotroph adenoma cell lines and rat and mouse normal adenohypophyses." (PMID 23555615, 2013). "The average methylation level for the RASSF3 gene promoter determined by pyrosequencing technology in human somatotroph adenomas was significantly higher than that in normal human adenohypophyses." (PMID 23555615, 2013). "Promoter hypermethylation of the RASSF3 gene correlated with downregulation of mRNA expression in human somatotroph adenomas." (PMID 23555615, 2013). "RASSF3 expression level was significantly lower in human somatotroph adenomas than in normal adenohypophyses." (PMID 23555615, 2013). "In our studies, there was a significant correlation between RASSF3 expression and promoter methylation in human pituitary somatotroph adenomas." (PMID 23555615, 2013). "Methylation and expression of RASSF3 in rat and mouse normal pituitary samples and somatotroph adenoma cell lines." (PMID 23555615, 2013). "To study the effect of RASSF3 on somatotroph adenomas, we transfected RASSF3 into GH3 and GT1.1 cells." (PMID 23555615, 2013). "In summary, our results suggest that RASSF3 gene silencing by promoter methylation is an important early event in somatotroph adenoma tumorigenesis." (PMID 23555615, 2013). "To understand the relation between RASSF3 methylation and somatotroph adenoma tumorigenesis, we studied RASSF3 methylation status by DNA bisulfite treatment and pyrosequencing analysis in human adenohypophyses and somatotroph adenomas." (PMID 23555615, 2013). "In somatotroph adenoma cell lines rat GH3 and mouse GT1.1, promoter hypermethylation and loss of RASSF3 was also observed compared to rat or mouse normal adenohypophyses." (PMID 23555615, 2013). "In the context of the data presented in this study, 5-Aza induced re-expression of RASSF3 might offer new avenues for treatment of somatotroph adenomas." (PMID 23555615, 2013). "The results of demethylation treatment indicate that RASSF3 expression is regulated by its gene promoter methylation status, and suggest that its silencing in somatotroph adenomas might be a result of hypermethylation." (PMID 23555615, 2013). "RASSF3, the smallest member of the RASSF family, had frequent methylation of CpG islands in its promoter regions in somatotroph adenomas but rarely in normal adenohypophyses." (PMID 23555615, 2013). "In our NimbleGen HG18 CpG Promoter Microarray study, the promoter of RASSF3 was frequently methylated in somatotroph adenomas but not in normal adenohypophyses." (PMID 23555615, 2013).
adenoma (1 paper, 2013). A neoplasm arising from the epithelium. "RASSF3 hypermethylation and downregulation was also observed in rat GH3 and mouse GT1.1 somatotroph adenoma cell lines." (PMID 23555615, 2013).
bone osteosarcoma (1 paper, 2024). A usually aggressive malignant bone-forming mesenchymal neoplasm arising from the bone. "Similarly, no endogenous RASSF3 or RASSF8 were detected in U2OS cells, a human bone osteosarcoma epithelial line that is highly efficacious to study Hippo signaling." (PMID 39009833, 2024).
colon tumors (1 paper, 2013). "RASSF3 is ubiquitously expressed in normal tissues, and downregulated in human lung, uterus and colon tumors." (PMID 23555615, 2013).
glioma (1 paper, 2012). A benign or malignant brain and spinal cord tumor that arises from glial cells (astrocytes, oligodendrocytes, ependymal cells). "Although the 5′ CpG island of RASSF3 has been identified earlier, RASSF3 does not show methylation in glioma tumor cell lines." (PMID 22530128, 2012).
lung carcinoma (1 paper, 2017). "Rassf3 is a tumor suppressor and its expression is downregulated in several human tumors, including liver, stomach, colon and lung cancers." (PMID 28351387, 2017).
pituitary adenomas (1 paper, 2013). "To understand the function of RASSF3 in pituitary adenomas, we overexpressed and knocked down RASSF3 in GH3 and GT1.1 cells." (PMID 23555615, 2013). "We next investigated RASSF3 mRNA level in the 27 pituitary adenomas and 4 normal pituitary tissues by qRT-PCR." (PMID 23555615, 2013). "However, as far as we are aware, there have been no studies about the mechanism of RASSF3 silencing or RASSF3 function in pituitary adenomas." (PMID 23555615, 2013).
prostate carcinoma (1 paper, 2023). A carcinoma that arises from epithelial cells of the prostate gland. "The tumor suppressor features of miRNA-642 was also confirmed by an alteration of expression of potential target genes, such as WT1, NUAK1, RASSF3, SKP2, GPS2 and IGFBP3, in prostate cancer." (PMID 37108073, 2023).
tumor (12 papers, 2012 to 2024). "For instance, in BM178, a number of significantly downregulated genes were observed on the chromosome arm rearranged by chromothripsis, including two tumor suppressors (the RASSF3 and RASSF9 members of the RAS-associated family of tumor suppressors; Fig5A)." (PMID 26415501, 2015). "B4GALT5 and IDH1 are associated with tumour growth and RASSF3 is a tumour suppressor gene." (PMID 36765842, 2023). "Outside of their recognition as tumor suppressors there are few functional data on RASSF3 or RASSF4." (PMID 39009833, 2024). "The reduced expression of RASSF3, a paralog of RASSF1 that has already been implicated as a tumour suppressor in UM, following treatment with trametinib is partially recovered by the addition of cerivastatin." (PMID 36765842, 2023). "Three of the RAS-association domain family members (RASSF2, RASSF3, and RASSF5) were involved in the network analysis using all methylomics decision tree models, which are known as tumor suppressor genes and epigenetically inactivated in different tumor types." (PMID 31552087, 2019). "RASSF3 suppression by Lenti-RASSF3 shRNA confirmed its function in tumor proliferation and apoptosis." (PMID 23555615, 2013). "Therefore, methylation-induced silencing of RASSF3 may promote tumor cell growth by inhibition of apoptosis and promotion of proliferation." (PMID 23555615, 2013). "Based on their functions, the literature and their occurrence within the candidate deleted FMCR, we propose RASSF3, IFNAR1, IFNAR2 and NFKBIA as novel candidate CRC tumour suppressor genes." (PMID 24367615, 2013). "To gain an insight into the contribution of gene promoter methylation toward aberrant expression of RASSF3, we studied RASSF3 methylation status and its expression level in normal rat and mouse normal adenohypophyses, and mouse GT1.1 and rat GH3 tumor cell lines." (PMID 23555615, 2013). "However, to the best of our knowledge, there have been no previous studies about the methylation status of RASSF3 in any tumor." (PMID 23555615, 2013). "However, the reduced expression of RASSF3 was not related to tumor grade." (PMID 23555615, 2013). "Investigated molecules without connection to common key tumor proteins are GNAS, USP8, USP48, HHIPL1, NNAT, RHOU, C5orf66 and RASSF3, which seem to be more specific biomarkers and therefore should be validated for concordant differences in liquid biopsies." (PMID 32498309, 2020).
cancer (5 papers, 2014 to 2024). A tumor composed of atypical neoplastic, often pleomorphic cells that invade other tissues. "RASSF3 is an oncogene and mutated in nearly one third of all human cancers." (PMID 31552087, 2019). "Methylation of RASSF1, RASSF2, RASSF3, RASSF6, RASSF7, and RASSF9, from the RASSF regulator family was strongly associated with expression of several GMDs in a variety of cancer categories." (PMID 33676569, 2021). "There have been comparatively few studies of RASSF3, RASSF4, and RASSF8, though it is clear their expression is downregulated in numerous human cancers." (PMID 39009833, 2024).
neurodegenerative disease (1 paper, 2024). A disorder of the central nervous system characterized by gradual and progressive loss of neural tissue and neurologic function. "Further investigation of how RASSF3 alters MIRO-microtubule interactions will shed light on how this GTPase-effector complex regulates the trafficking of these organelles, with significant implications for neurodegenerative diseases and other human disorders." (PMID 39009833, 2024).
RASSF3 also shares sentences with these, for which no sentence is quoted: Alzheimer disease (1 paper); gastric cancer (1); pituitary (1); prostate tumor (1).